MALAT1 (metastasis associated lung adenocarcinoma transcript 1)
Diseases named in the same sentence as MALAT1 in open-access papers (continued):
Sharing a sentence is not in itself a finding about the gene and the disease.
lung cancer (continued). "LncRNA metastasis-associated lung adenocarcinoma transcript 1 (MALAT1) was first discovered in lung cancer, and up-regulation of MALAT1 is negatively associated with survival time of lung cancer patients." (PMID 31404170, 2019). "In this study, we investigated the mechanism by which lncRNA metastasis-associated lung adenocarcinoma transcript 1 (MALAT1) mediates cisplatin resistance in lung cancer." (PMID 29484127, 2018). "These key lncRNAs included several known lung cancer lncRNAs, such as metastasis-associated lung adenocarcinoma transcript (MALAT1), LINC00261, and LINC01614 (top three rows)." (PMID 29303984, 2018). "For example, results of knockdown studies in lung cancer cells indicate that loss of MALAT-1 decreased migration/wound healing and injection of MALAT-1-deficient A549 lung cancer cells in mice resulted in significantly decreased formation of lung nodules." (PMID 29389953, 2018). "Malat1 was one of the first identified lncRNAs associated with human disease, which was originally described to be associated with metastasis of lung cancer." (PMID 29891768, 2018). "According to this literature, MALAT1 has been shown to be highly associated with metastasis of lung cancer and promote lung cancer cell motility by regulating motility related gene expression." (PMID 30046354, 2018). "The prototype candidate is the nuclear lncRNA MALAT1 which was originally identified as a metastasis-associated transcript in lung cancer." (PMID 30597925, 2018). "Several lncRNAs have been proposed as oncogenic in lung cancer, including MALAT1 (a diagnostic and prognostic biomarker in NSCLC), AK126698 (mediates cisplatin resistance in NSCLC), and lncRNA-DQ786227 (implicated in chemical carcinogenesis)." (PMID 29483846, 2018). "Lung cancer patients with high MALAT1 levels were associated with cisplatin resistance and low overall survival." (PMID 29484127, 2018). "MALAT1 is a potential prognostic and diagnostic biomarker in bladder cancer, lung cancer, nasopharyngeal carcinoma and osteosarcoma." (PMID 29484127, 2018). "MALAT1 represents a promising diagnostic biomarker detectable in blood, to effectively screen lung cancer." (PMID 28634418, 2017). "First, this study used a single-institution cohort to investigate the association between MALAT1 variant and the survival outcome of lung cancer patients for practical reason." (PMID 28253859, 2017). "Schmidt and the colleagues reported that the overexpression non-coding metastasis associated lung adenocarcinoma transcript 1 (MALAT1) can increase the lung cancer cell proliferation and migration activity." (PMID 28159929, 2017). "The lncRNA metastasis-associated lung adenocarcinoma transcript 1 (MALAT1) is initially up-regulated in lung cancer, which is reported to be a favorable prognostic factor for patients with stage I non-small cell lung cancer." (PMID 28187439, 2017). "Metastasis is the major cause of death from lung cancer, and MALAT1 was significantly associated with metastasis of early-stage NSCLC patients." (PMID 28253859, 2017). "In metastatic non‐small cell lung cancer, increased expression of metastasis‐associated lung adenocarcinoma transcript‐1 (MALAT1) correlates with poor prognosis and inhibition of MALAT1 expression reduces lung cancer metastasis." (PMID 27756687, 2017). "MALAT1 is a critical regulator of the metastasis phenotype of lung cancer cells, and associated with tumor invasion in non-small cell lung cancer." (PMID 29212230, 2017). "After adjusting for late stage and lymph node metastasis using multivariate Cox regression analysis, co-overexpression of Oct4, NEAT1 and MALAT1 in lung cancer patients showed a relative risk of death of 2.42 (P = 0.039)." (PMID 28615056, 2017). "Although MALAT1 expression in lung cancer tissue was reported to be associated with poor prognosis in lung squamous cell carcinoma, our findings indicated that the SNP rs3200401 cannot affect the survival outcome of lung squamous cell carcinoma patients." (PMID 28253859, 2017).
lung cancer (continued). "The lncRNA metastasis associated lung adenocarcinoma transcript 1 (MALAT1) played a vital role in metastasis formation in lung cancer and was a potential therapeutic target." (PMID 28915709, 2017). "High level of MALAT1 has been reported to associate with lung cancer metastasis, which is crucially related to poor prognosis." (PMID 28415568, 2017). "Previously, the important roles of metastasis-associated lung adenocarcinoma transcript 1 (MALAT1) in lung cancer have been well established." (PMID 29212230, 2017). "HOTAIR and MALAT1 probably are the two most comprehensively studied cancer related lncRNA, whose increased expression are associated with lung cancer progression, metastasis, chemo-resistance and relapse, resulting in patients’ poor prognosis and survival." (PMID 29137177, 2017). "Metastasis associated in lung adenocarcinoma transcript 1 (MALAT1), a lncRNA that was first recognized as a prognostic parameter for patient survival of stage I lung cancer, is up-regulated in multiple human malignancies, including breast cancer." (PMID 27191888, 2016). "The metastasis-associated lung adenocarcinoma transcript 1 (MALAT1), the first lncRNA identified as an independent prognostic marker for nonsmall-cell lung cancer, was found to play an important role in the metastasis of various types of cancers." (PMID 27259250, 2016). "MALAT1 was discovered as a prognostic marker for lung cancer metastasis but also has been linked to several other human tumor entities." (PMID 27782152, 2016). "MALAT1 (metastasis-associated lung adenocarcinoma transcript 1) is a predictive marker for metastasis development in lung cancer." (PMID 27782152, 2016). "For example, elevated expression of metastasis-associated lung adenocarcinoma transcript 1 (MALAT1) is associated with lung cancer progression and metastasis." (PMID 25863539, 2015). "LncRNA metastasis-associated lung adenocarcinoma transcript 1 (MALAT1) located on chromosome 11q13 has recently been identified to be involved in tumorigenesis of several cancers such as lung cancer, pancreatic cancer, and cervical cancer." (PMID 26461224, 2015). "MALAT1 (metastasis-associated lung adenocarcinoma transcript 1) was discovered as a prognostic marker for lung cancer metastasis but also has been linked to several other human tumor entities." (PMID 26136615, 2015). "LncRNA metastasis-associated lung adenocarcinoma transcript 1(MALAT1) has recently been identified to be involved in tumorigenesis of several cancers such as lung cancer, bladder cancer and so on." (PMID 26461224, 2015). "MALAT1 overexpression in tumor tissue has been particularly linked to lung cancer, colorectal cancer, gastric cancer, and hepatocellular carcinoma (HCC)." (PMID 26516918, 2015). "In lung cancer, MALAT1 regulates a series of metastasis-associated genes, and thus the migratory ability of MALAT1-deficient cells is impaired." (PMID 26420912, 2015). "For example, metastasis-associated lung adenocarcinoma transcript 1 (MALAT-1) appears to be a potential diagnostic and prognostic marker of non–small cell lung cancer." (PMID 26447755, 2015). "The long noncoding RNA MALAT1, also known as NEAT2, is over-expressed in metastatic, compared with primary, lung cancer tissues, and is associated with poor prognosis in patients with non-small cell lung cancer." (PMID 24742640, 2014). "The lncRNAs controlled by MRTF–SRF signaling include Tug1 and Malat1/Neat2 (a lncRNA implicated in lung cancer cell invasion and metastasis), which are recruited by unmethylated and methylated PC2, respectively." (PMID 24732378, 2014). "We selected the human lung carcinoma cell line, A549, to investigate the in vitro consequences of MALAT1 deficiency for apoptosis sensitivity and proliferation potential." (PMID 23717670, 2013). "MALAT1 is currently the only lncRNA with prognostic significance in lung cancer and is associated with high metastatic potential and poor patient prognosis in NSCLC." (PMID 22852089, 2012).
lung cancer (continued). "MALAT1, also known as NEAT2 (nuclear-enriched abundant transcript 2), was the lncRNA that was originally found to be associated with lung cancer." (PMID 23109937, 2012). "At this time, a handful of lncRNAs have been associated with lung cancer, most significantly metastasis-associated lung adenocarcinoma transcript 1 (MALAT1), a lncRNA that is associated with high metastatic potential and poor patient prognosis in NSCLC." (PMID 22852089, 2012). "Additional lncRNAs whose expression has been shown to be deregulated in lung carcinoma include H19, which undergoes loss of imprinting and overexpression, MALAT-1, cancer up-regulated drug resistant (CUDR), and BC200." (PMID 22852089, 2012). "The high expression of MALAT1 is associated with metastasis and poor prognosis in lung cancer." (PMID 41394878, 2025). "While MALAT1 may have a less direct role in this cell death pathway in liver cancer, it may affect lung cancer patients' responsiveness to medicines that cause cuproptosis by controlling genes associated with mitochondrial activity." (PMID 39325172, 2024). "Additionally, MALAT1 has also been used as a biomarker for lung cancer metastasis using a loss-of-function model demonstrates that MALAT1 has an active role in regulating gene expression that is responsible for preventing lung cancer metastasis." (PMID 38517388, 2024). "Metastasis Associated Lung Adenocarcinoma Transcript-1(MALAT1) is one of the abundantly distributed lncRNA in several tissues and is often found elevated in various cancers including metastasis lung cancer, breast cancer, and metastasis non-small cell lung cancer." (PMID 38132140, 2023). "MALAT1 was first found to be involved incarcinogenesis in patients with nonsmall cell lung cancer and was shown to beassociated with a higher risk of metastatic disease and unfavorable outcome inpatients with squamous cell cancer and adenocarcinoma of the lung." (PMID 37538803, 2023). "Different mechanisms have been attributed to metastasis-associated lung adenocarcinoma transcript 1 (MALAT-1), which may promote angiogenesis in endothelial ovarian carcinoma and in lung cancer." (PMID 37108672, 2023). "Furthermore, a high degree of HOTAIR and MALAT1 expression is linked to unfavorable prognoses in individuals with lung cancer." (PMID 38011277, 2023). "The lung transcriptomic data of EMR mice show changes in the expression of genes previously identified in lung cancer cells, including metastasis associated in lung denocarcinoma transcript 1 (Malat1), synaptotagmin 7 (Syt7), and tubulin beta 3 class III (Tubb3)." (PMID 35619714, 2022). "Next, we took the MALAT1 gene as an example for further analysis to verify whether it might be associated with lung cancer." (PMID 35882886, 2022). "For instance, MALAT1 can function through sponging miRNAs, thus serving as a competitive endogenous RNA, in nasopharyngeal carcinoma and gastric cancer; alternatively, it can regulate transcription of a set of metastasis-associated genes in lung cancer." (PMID 36563164, 2022). "Therefore, the study recruited Chinese Northeast Han Population as the research objects and performed a case-control study to explore the association between MALAT1 polymorphisms and susceptibility of lung cancer." (PMID 35928715, 2022). "In addition, the association of MALAT1 RNA level with prognosis of lung cancer was also analyzed using Kaplan–Meier plotter database." (PMID 34308750, 2021). "ShRNA specifically designed to silence MALAT1 was used to investigate whether the expression level of MALAT1 was associated with the proliferation, metastasis and invasion abilities of lung cancer cells." (PMID 34257576, 2021). "Moreover, the finding confirmed that the lung cancer metastasis-associated lung adenocarcinoma transcript 1 (MALAT1) and the lncRNA smoke- and cancer-associated lncRNA-1 (SCAL1) are good candidates." (PMID 34573278, 2021).
lung cancer (continued). "Previous studies have demonstrated that lncRNAs such as HOTAIR (Hox transcript antisense intergenic RNA) and MALAT1 (metastasis-associated lung adenocarcinoma transcript 1) are upregulated in lung cancer; are associated with enhanced proliferation and metastasis; and predict poor prognosis." (PMID 34106559, 2021). "lncRNA metastasis–associated lung adenocarcinoma transcript 1 (MALAT1) was first found in early-stage non–small-cell lung cancer, and it could be a diagnostic factor to observe the metastasis of early non–small-cell lung cancer." (PMID 33995063, 2021). "In the present meta‐analysis, the results showed that the sensitivity and specificity of serum MALAT1 in the diagnosis of lung cancer were 0.81 and 0.67, respectively, and the AUC was 0.6, indicating that the detection of MALAT1 in circulating blood was of high diagnostic value for lung cancer." (PMID 31846184, 2020). "Furthermore, another study on lung cancer observed reduced MALAT1 promoter methylation, which is subsequently associated with increased MALAT1 expression." (PMID 32099603, 2019). "Moreover, metastasis associated lung adenocarcinoma transcript 1 (Malat1) regulates SP1 downstream protein expression in lung cancer by enhancing the stability and transcriptional activity of SP1." (PMID 30744670, 2019). "MALAT-1, one of the first lncRNAs, was demonstrated to be associated with lung cancer." (PMID 30352575, 2018). "We revealed that high MALAT1 expression is associated with poorer prognosis of lung cancer; here we further investigated whether MALAT1 is associated with the chemo-resistance of lung cancer cell." (PMID 29212230, 2017). "Also, metastasis-associated lung adenocarcinoma transcript 1 (MALAT1) is highly expressed in lung cancer." (PMID 27999202, 2017). "However, the associations between genetic polymorphisms of lncRNA MALAT1 and lung cancer prognosis were less investigated." (PMID 28253859, 2017). "Recently studies have demonstrated that the long non-coding RNA (lncRNA) metastasis associated lung adenocarcinoma transcript 1 (MALAT1) may participate in the development and progression of lung cancer." (PMID 28253859, 2017). "For example, promotion of lung cancer metastasis by lncRNA MALAT1 (Metastasis Associated Lung Adenocarcinoma Transcript 1); control of hepatocellular cancer cell growth and apoptosis by MEG3; regulation of oesophageal adenocarcinoma cell proliferation and migration by HNF1A-AS1." (PMID 28069000, 2017). "MALAT1 is a type of long non-coding RNA associated with lung cancer and breast cancer." (PMID 28938549, 2017). "Metastasis-associated lung adenocarcinoma transcript 1 (MALAT-1), a long, non-coding nuclear RNA, is known as a poor prognostic marker and a predictive marker for metastasis development in lung cancer; it targets genes involved in cell migration, tumor growth and the EMT." (PMID 28806747, 2017). "Moreover, Oct4-mediated high expression of lncRNAs such as nuclear paraspeckle assembly transcript 1 (NEAT1) and metastasis-associated lung adenocarcinoma transcript 1 (MALAT1) promoted lung cancer cell proliferation, migration and invasion abilities." (PMID 28615056, 2017). "Although the role of MALAT1 was associated with lung cancer progression and prognosis, whether it is involved in the chemo-resistance of lung cancer cell and the underlying mechanism still remains unclear." (PMID 29212230, 2017). "Metastasis-associated lung adenocarcinoma transcript 1 (MALAT-1) may promote lung cancer metastasis to the brain via epithelial-mesenchymal transition, and was both highly expressed and associated with poor prognosis in NSCLC." (PMID 27903974, 2017). "Differential expression profiling has also led to the discovery of the nuclear lncRNA metastasis-associated lung adenocarcinoma transcript 1 (MALAT1), as one of the first lncRNAs to be ascribed a role as a potential prognostic biomarker for lung cancer survival." (PMID 27626181, 2016).
lung cancer (continued). "For example, lncRNA metastasis-associated lung adenocarcinoma transcript 1 (MALAT1) is a highly conserved nuclear lncRNA, which is up-regulated and could be a predictive marker for metastasis development in lung cancer." (PMID 26840083, 2016). "For example, MALAT1 is shown to modulate the expression of several of the cell motility and metastasis-associated genes at the transcriptional and/or post transcriptional level in lung cancer." (PMID 27250026, 2016). "MALAT1 not only has a crucial significance in predicting metastasis risk and may be a promising therapeutic target in treating lung cancer, but also can be a diagnostic biomarker detectable in blood to screen lung cancer." (PMID 27143813, 2016). "MALAT1 has been shown to promote cell proliferation, cell migration and cell invasion of neuroblastoma cell lines, which is consistent with the metastatic property of MALAT1 implicated in lung cancer." (PMID 26087192, 2015). "The most well-characterized lncRNA reported in lung cancer is MALAT1 (metastasis-associated lung adenocarcinoma transcript 1), which is associated with high metastatic potential and poor patient prognosis in non-small cell lung cancer patients with and without metastatic tumors." (PMID 25116943, 2014). "Similarly, high expression of the nuclear speckle associated lncRNA metastasis-associated lung adenocarcinoma transcript 1 (MALAT1) modulates alternative splicing and has been associated with metastasis and poor outcome in patients with lung cancer." (PMID 21991387, 2011). "Moreover, MALAT1 is implicated in the progression of various malignant tumors beyond lung cancer." (PMID 40597438, 2025). "We also show the possibility that inhibiting MALAT1 may significantly diminish tumor size in animal models, thereby presenting novel diagnostic and treatment strategies for lung cancer in AAs and potentially mitigating racial disparities in lung cancer prognosis." (PMID 38791954, 2024). "Single nucleotide polymorphisms (SNPs) in MALAT1 gene might be predictive markers for lung cancer." (PMID 35928715, 2022). "However, few studies have investigated about MALAT1 polymorphisms and the risk of lung cancer." (PMID 35928715, 2022). "In lung cancer, MALAT1 actively regulates the expression of a set of metastasis-associated genes, MALAT1-deficient cells show decreased migration and form fewer tumor nodules in mice, and antisense oligonucleotides targeting MALAT1 prevent metastasis formation after tumor cell implantation in mice." (PMID 32174966, 2020). "For certain lncRNAs closely related to lung cancer progression, such as MALAT1 and HOTAIR, small interfering RNA (siRNA) or short hairpin RNA (shRNA) can be designed to inhibit their expression, thereby affecting the biological behavior of cancer cells." (PMID 41394878, 2025). "Previous research showed that overexpression of TDP-43 stimulated an increase in MALAT1 RNA expression level, while knockdown of TDP-43 caused a decrease in MALAT1 RNA level in A549 lung cancer cells." (PMID 39837396, 2025). "By detecting the expression level of MALAT1 in lung cancer tissues or patient plasma, the metastatic potential of lung cancer and the prognosis of patients can be assessed." (PMID 41394878, 2025). "Oct4 transcriptionally activates the expression of NEAT1 and MALAT1 to accelerate the progression of lung cancer." (PMID 40115023, 2025). "Compared to normal lung cells or tissues, lung cancer cells or tissues have fewer methylated forms of MALAT-1 promoter revealing that DNA methylation is necessary for MALAT-1 expression." (PMID 39912974, 2025). "The highly invasive subline of lung cancer cells that metastasize to the brain has elevated MALAT-1." (PMID 39912974, 2025). "Fang et co-workers observed that a high expression level of MALAT1 is observed in cisplatin-resistant lung cancer." (PMID 40352931, 2025).